HIF1A (hypoxia inducible factor 1 subunit alpha)
Diseases named in the same sentence as HIF1A in open-access papers (continued):
Sharing a sentence is not in itself a finding about the gene and the disease.
glioma (continued). "Glioma hypoxic microenvironment and acidosis stimulate the HIF-1α expression, which may result in upregulation of NHE1 expression and promote the acidic microenvironment." (PMID 30262908, 2018). "HIF1A accumulation leads to PDL1 up-regulation in glioma cell lines." (PMID 30393513, 2018). "However, further studies are needed to assess whether the reduction in PC and PE levels induced by HIF-1α is mechanistically linked to the reduction in PtdCho and PtdE levels in IDHmut gliomas and, conversely, whether ER-phagy contributes to the reduction in PC and PE levels in IDHmut gliomas." (PMID 29619216, 2018). "It is therefore possible that, in IDHmut gliomas, HIF-1α downregulates CK activity." (PMID 29619216, 2018). "In this study, some important glioma-related genes were not differentially expressed in PDGFRA-overexpressing canine gliomas, including HIF1-α, CTLA4, DLL3, and TNFRSF12A, important mediators of angiogenesis, immune evasion, self-renewal, and invasion in the tumor microenvironment." (PMID 29352201, 2018). "In a related study, CD133+ glioma cells were increased through HIF-1α activation under hypoxic condition, which may also be mediated by AKT of the ERK1/2 pathway." (PMID 30382122, 2018). "Tipifarnib reduces the levels of HIF1α in U87 glioma xenografts by increasing oxygen levels." (PMID 30486451, 2018). "Furthermore, we and others previously demonstrated that HIF-1α levels are post-translationally stabilized in IDHmut gliomas as a result of 2-HG-mediated inhibition of the activity of the prolyl hydroxylases that target HIF-1α for degradation." (PMID 29619216, 2018). "In addition to hypoxia, HIF-1α can also be activated in response to protoinflammatory mediators such IL-1β and plays a key role in glioma progression." (PMID 28781970, 2017). "Therefore, we presume that TFF3 regulates the transcriptional activity of HIF-1α and thus promotes glioma cells proliferation, migration and invasion." (PMID 29100347, 2017). "Furthermore, HIF1α promotes a significant phenotypic shift towards an undifferentiated population through dedifferentiation from normal glioma cells after TMZ treatments." (PMID 28801626, 2017). "Overall, these findings confirm that F2 may target HIF-1α and induce anti-glioma effects in both cell culture and tumor xenograft models." (PMID 29156717, 2017). "Moreover, knockdown of HIF-1α decreased VEGF expression in U87 cells under normoxic and hypoxic conditions, indicating that VEGF is regulated by HIF-1α, and inhibition of angiogenesis is one anti-glioma mechanism of F2 in U87 cells." (PMID 29156717, 2017). "Recently we demonstrated, in a glioma pre-clinical model, a loop between HIF1α and miR-675-5p." (PMID 28061476, 2017). "This study indicates that normal glioma cells and GSCs may be transformed through dedifferentiation and differentiation regulated by HIF1α under different oxygen levels, which therefore influence the sensitivity of glioma cells to chemotherapy." (PMID 28801626, 2017). "Therefore, identifying HIF1α-targeted molecules will provide further understanding in the development and treatment of human glioma." (PMID 28754121, 2017). "As the only oxygen-regulated subunit, HIF-1α activation is also controlled by multiple oncogenic pathways, which involve loss of tumor suppressor genes, such as PTEN and growth factor signaling, both of which are common alterations found in gliomas." (PMID 29156717, 2017). "Moreover, the mean IC50 values were enhanced after HIF1α over-expression in glioma cells compared with the control." (PMID 28801626, 2017). "In addition, knock down of HIF-1α in glioma cells impairs their ability to migrate and invade, and also increases the sensitivity of cells to chemotherapy and inhibits the self-renewal of glioma stem cells (GSCs)." (PMID 29156717, 2017).
glioma (continued). "POSTN gene encodes for periostin; an extracellular protein secreted by glioma cancer stem cells that recruits macrophages to the CSC niche, promotes angiogenesis (in part by increasing HIF-1α expression), cell invasion and glioblastoma progression in mouse models." (PMID 28472177, 2017). "Likewise, TFF3 expression correlates with the WHO grade of glioma, regulating the expression and transcriptional activity of HIF-1α under normoxic conditions." (PMID 29100347, 2017). "The HIF-1α expression domain became more disperse in glioma specimens with high levels of hypoxia." (PMID 27602954, 2016). "However, the action of the Nrf2 connection is not restricted to the digestive tract since knockdown of Nrf2 in glioma cells suppressed glioblastoma angiogenesis in vitro and in xenotransplanted mice by inhibiting HIF-1α." (PMID 27286880, 2016). "Akin to HIF-1α, high Lon expression correlated with high-grade glioma tumors." (PMID 27764809, 2016). "The congregation of these macrophage chemotactic factors in perivascular niche areas may partially explain the accumulation of TAMs around vessels in low HIF-1α glioma specimens." (PMID 27602954, 2016). "As HIF-1α positive regions expanded, more non-glioma stem-like cells began to express POSTN." (PMID 27602954, 2016). "The high rate of POSTN expression in GSLCs in low HIF-1α glioma specimens may explain this POSTN distribution pattern." (PMID 27602954, 2016). "Taken together, these results suggest that HIF-1α can also inhibit glioma growth and progression." (PMID 25893706, 2015). "Interestingly, increased CIDEA levels triggered glioma cell apoptosis, decreased HIF-1α activation and elevated PPARγ levels." (PMID 27551468, 2015). "Our study also indicates that HIF-1α is a potent inducer of glioma invasion." (PMID 25893706, 2015). "Moreover, some downstream pathway proteins, such as p-AKT, p-ERK1/2 and HIF-1α were significantly suppressed by miR-143 in glioma tissues." (PMID 24980823, 2014). "Furthermore, we evaluated the effect of EPCs on HIF-1α, Notch1, Flk1, and p-Flk1 expressions in tumors and cultured C6 glioma cells via EPCs transplantation or EPCs-CM treatment, respectively." (PMID 24722469, 2014). "In addition, an investigation with a proteomic approach supports the possibility that the dipeptide L-carnosine affects tumour cell growth in the human glioma cells by interfering with protein folding/processing or with HIF-1α signalling." (PMID 24804733, 2014). "Based on this evidence, it is reasonable to suggest that the refractory accumulation of HIF-1α in the nucleus of glioma cells following reoxygenation and subsequent return to hypoxia in our models is at least partly due to an upregulation of PHD2 and PHD3 activity." (PMID 25350400, 2014). "As we showed before, HIF-1α, Notch1, and Flk1 may be important factors for C6 glioma cells transdifferentiation." (PMID 24722469, 2014). "In addition, hypoxia promoted expansion of the CD133-positive glioma stem cells through activation of HIF-1α, and the CD133 expression level was increased under the chemical hypoxia in renal cancer cell lines." (PMID 23840432, 2013). "HIF-1α activity has been implicated in the induction of epithelial to mesenchymal transition, and downregulation of HIF-1α expression has been reported to suppress glioma, colon cancer and melanoma cell migration in vitro." (PMID 23740575, 2013). "ATRA significantly increased the level of HIF-1α mRNA in glioma cells." (PMID 23554794, 2013). "HIF-1α has been described to be over-expressed in various cancers including gliomas." (PMID 22134773, 2012). "Therefore, the introduction of Egln3 into Hu- and Rt-glioma cells was biased to uncouple the hypoxia-initiated adaptive responses mediated by Hif-2α relative to Hif-1α." (PMID 22905089, 2012). "The gene expression analysis identified genes and pathways that might further elucidate the role of HIF-1α in glioma invasion." (PMID 20515450, 2010).
glioma (continued). "Finally, expression profiling experiments in glioma cells provided detailed insight into a broad range of specific biological pathways and processes downstream of HIF-1α." (PMID 20515450, 2010). "The clonogenic assay was also applied to determine whether HIF-1α-siRNA or CTM sensitized glioma cells U251MG and U343MG to radiation." (PMID 21050481, 2010). "To further elucidate the functional role of HIF-1α in glioma cell migration in vitro and in invasion in vivo, we used a shRNA approach to knock down HIF-1α expression complemented with genome-wide expression profiling, performed in both normoxic and hypoxic conditions." (PMID 20515450, 2010). "Under hypoxic conditions, all glioma cell lines used as a control showed induction of HIF-1α." (PMID 20515450, 2010). "HIF-1a promotes CD133-positive human glioma-derived CICs propagation and self-renwal." (PMID 20979610, 2010). "However, the synergistic regulation of glioma malignancy by HIF1α and HIF2α has been less explored." (PMID 40290443, 2025). "Additionally, further investigation of the regulatory effects of HIF-1α on ferroptosis-related molecules in glioma cells revealed that HIF-1α overexpression decreased LPO levels and increased GSH concentrations, counteracting the ferroptosis-promoting effects of PAX6." (PMID 41154694, 2025). "Similarly, the use of GA disrupted the interaction between HSP90 and its substrates EF-2 kinase and HIF-1α in different glioma cell lines, resulting in reduced cells’ clonogenicity and migration ability, and inhibiting the growth of glioma xenografts in nude mice." (PMID 41002413, 2025). "The association between HIF-1α and the regulation of ferroptosis in gliomas has not been reported." (PMID 41154694, 2025). "Also, evofosfamide decreases the tumor volume and weight in murine glioma xenograft models, and higher levels of HIF1α, PDHK1, G6P, F6P, DHAP, 3PG, PEP, Pyr, and lactate in tumor tissue induce an increase in the overall survival in the treated animals in relation to the control group." (PMID 38786726, 2024). "Finally, other mechanisms such as HIF-1α may also be involved, as the inhibitory effects of 2ME on glioma growth were accompanied by the inhibition of HIF-1α; however, this could not be tested in our study." (PMID 38994940, 2024). "However, the inactivation of HIF1 with evofosfamide inhibits the GLUT1, PDHK, HIF1α, lactate, and glycolytic ATP leading to a decrease in the total ATP levels and a high rate of apoptosis of canine glioma cells in a hypoxic medium with respect control cells without treatment." (PMID 38786726, 2024). "Moreover, the combination of PX-478 with the ferroptosis-inducing agent SAS had a synergistic anticancer effect in both in vitro and in vivo models, suggesting a potential therapeutic strategy for sensitizing glioma cells to ferroptosis through targeting the PI3K/AKT/HIF-1α/SLC7A11 axis." (PMID 38562143, 2024). "Therefore, therapeutic strategies based on inhibition of the HIF-1α/LAMC1 axis to disrupt the tumor hypoxic microenvironment may be a promising approach for glioma treatment." (PMID 38678297, 2024). "When focusing on gliomas, we found that the high expression of HIF-1α accompanied by poor prognosis, higher clinical grade, as well as the status of 1p19q codeletion and IDH mutation; These findings are consistent with previous reports regarding high HIF-1α levels and poor outcome in gliomas." (PMID 38678297, 2024). "The association between PD-L1 expression and hypoxia was also documented in a study on 120 glioma patients’ tissues, in which the PD-L1 expression (positive in 42% tumors, mostly overexpressed in high grade gliomas) was significantly related to high HIF-1α expression." (PMID 37958373, 2023). "Those genes could reduce glioma cells invasion and migration by the HIF-1α pathway." (PMID 36334237, 2023). "Therefore, we speculate that the effect of silvestrol in inhibiting glioma may be an oxygen-dependent and related to HIF1α." (PMID 35677890, 2022).
glioma (continued). "Our previous studies also evidenced that the malignant progression of glioma was related to the HIF-1α and vascular endothelial growth factor (VEGF), and silencing of HIF-1α by siRNA application could enhance the radiation sensitivity of human glioma growth in vitro and in vivo." (PMID 35607406, 2022). "Therefore, we performed a series of experiments to verify whether HIF1α, HIF2α and Sox2 regulated glioma cell dedifferentiation under hypoxic conditions." (PMID 34976166, 2022). "Therefore, we unexpectedly identified both HIF1α and HIF2α as critical targets in glioma." (PMID 34976166, 2022). "In conclusion, HIF-1α inhibition by using novel PI3K inhibitors combined with 14-3-3β knockdown by specific siRNA may represent an efficient therapeutic strategy to treat patients with glioma." (PMID 35607406, 2022). "Therefore, it can be speculated that CA inhibits glioma progression via the Pi3k/Akt pathway, and Hif-1α and Sept9 exhibit the same trend." (PMID 35096204, 2022). "Previously, CLK1 could modulate the chemoresistance of glioma cells via glycolytic signaling mediated by AMPK/mTOR/HIF-1α as well as participating in modulating the splicing process of gastric cancer, serving as an underlying therapeutic target against this malignancy." (PMID 35832557, 2022). "Interestingly, baicalein decreased the protein expression of HIF-1α in U87 gliomas." (PMID 33401572, 2021). "Thus, the activity of Smad3 and HIF-1α could represent the main molecular targets for treatment of gliomas because these proteins may coordinate the basic aspects of cancer stem cell biology." (PMID 34707087, 2021). "Therefore, we speculated that HAX1 served as downstream of HIF‐1α to regulate glioma cell in hypoxia." (PMID 34755451, 2021). "Therefore, we hypothesized that borneol induces autophagy in glioma cells by targeting the mTORC1/eIF4E signaling pathway, which in turn downregulates HIF-1α and sensitizes the cells to radiotherapy." (PMID 34917504, 2021). "Therefore, HIF1A could potentially be involved in the functions of OR7E156P on glioma cell aggressiveness." (PMID 34422645, 2021). "Furthermore, HIF-1α has been suggested as a potential therapeutic target using small interference (si)RNA, packaged in a novel surfactant-based nucleic acid carrier and delivered into gliomas of an In vivo orthotopic mouse model by osmotic pumps." (PMID 34073734, 2021). "Finally, a co-culture model of glioma cells with normal astrocytes suggests that astrocyte-mediated production of CCL20 facilitates CCR6-expressing GBM cell adaptation to hypoxic TME via upregulation of hypoxia-inducible factor 1-alpha (HIF1-α)." (PMID 35008294, 2021). "HIF‐1α could increase the expression of HAX1 to protect glioma cell in hypoxia." (PMID 34755451, 2021). "To further investigate whether HAX1 serves as a downstream of HIF‐1α to maintain the survival ability and characteristics of glioma, we established LV3‐pGLV‐H1 + Puro plasmids with pcDNA‐HAX1 or control oligonucleotides (Lenti‐HAX1 and Lenti‐NC) to overexpress HAX1 protein expression." (PMID 34755451, 2021). "The up-regulation of lncRNA H19 in glioma cells, suggested it could function as one of the ceRNAs for miR-138, and thus promote angiogenesis, invasion, migration, and proliferation by increasing HIF-1α expression." (PMID 34646821, 2021). "Besides, EMT pathways could cross talk with the PI3K/Akt/GSK3β pathway in glioma, through HIF-1α, PTEN, and the WNT/β-catenin pathways." (PMID 33029523, 2020). "Also, in glioma cells Nodal was shown to increase HIF1α activity." (PMID 31632347, 2019). "We predict that HIF1A/PDL1 axis may be overactivated in glioma cells after treatment with MLN4924." (PMID 30393513, 2018). "Thus TMZ-mediated stimulation of HIF-1α activity may be responsible for upregulating NHE1 expression in glioma." (PMID 30262908, 2018).
glioma (continued). "Hypoxia-inducible factor-1α (HIF1α) contributes substantially to the stemness maintenance of GSCs and resistance of glioma to chemotherapy; thus, we investigated whether HIF1α regulates the resistance or sensitization of glioma cells to chemotherapy in different oxygen levels." (PMID 28801626, 2017). "However, whether HIF-1α increases PLOD2 expression by directly binding to HREs or whether PLOD2 is involved in hypoxia-mediated glioma tumorigenesis still remains unclear." (PMID 28410212, 2017). "Hence, HIF-1α is an attractive target for the development of novel anti-glioma agents." (PMID 29156717, 2017). "Therefore, we hypothesized that hypoxia inducible factor-1α (HIF-1α) up-regulates ICAM-1 expression in glioma cells." (PMID 29228586, 2017). "Thus, inhibition of TFF3 may offer a selective therapeutic strategy for targeting expression of HIF-1α in gliomas." (PMID 29100347, 2017). "The result suggested that TFF3 could bind to HIF-1α in glioma cell lines." (PMID 29100347, 2017). "Based on these findings, we hypothesized in this study that stem-like glioma cells showing HIF-1α-regulated quiescence are a strong candidate for long-term tumorigenic cells, and we tried to visualize these cells and their niches histologically in clinical tissue samples of astrocytic tumors." (PMID 26799577, 2016). "Thus, CIDEA negatively regulates HIF-1α activation in glioma cells." (PMID 27551468, 2015). "The 3-(5-hydroxymethyl-2-furyl)-1-benzylindazole (YC-1)-induced inhibition of HIF-1α has been found to downregulate the VM formation of glioma cells under hypoxic conditions; other pathways, aside from the HIF-1α pathway, may also affect the VM formation of glioma cells." (PMID 25667663, 2015). "Therefore, we examined whether HIF-1α forms a complex with β-catenin in glioma cells by performing co-IP experiments." (PMID 24650032, 2014). "HIF-1α knockdown by siRNA or antisense techniques has been shown to suppress cell growth, proliferation and migration in both normal human cells and malignant tumor cells, including umbilical vascular endothelial cells, medulloblastoma, prostate cancer and glioma." (PMID 23289374, 2013). "Notably, HIF-1α promotes CD133-positive human glioma-derived CICs propagation and self-renewal." (PMID 22140506, 2011). "In addition, knockdown of HIF-1α by RNA interference attenuates human glioma cell growth in vivo." (PMID 21050481, 2010). "tRF-22 negatively regulates MAX dimerization protein 1 (MXD1) expression by binding to its 3′UTR, thereby weakening MXD1's transcriptional suppression of hypoxia-inducible factor 1 alpha (HIF1A) and promoting glioma vascular mimicry (VM) formation." (PMID 41550494, 2026). "We analyzed the expression and correlation of HIF1α, HIF2α, and IGF1R in glioma using The Cancer Genome Atlas (TCGA) and Chinese Glioma Genome Atlas (CGGA) databases." (PMID 40290443, 2025). "HIF1α, HIF2α, CD133, and CD15 were highly expressed in the hypoxic microenvironment of glioma cells according to reverse transcription quantitative PCR (RT–qPCR) and western blotting results." (PMID 40370575, 2025). "In the ROC analysis, the threshold values of the serum GAL-1, GAL-8, ITGβ-1, HIF-1α, and MMP-9 levels for diagnosing glioma were 41.83 ng/mL, 8.28 ng/mL, 436.34 pg/mL, 1411.00 pg/mL, and 450.08 ng/mL, respectively." (PMID 40512281, 2025). "Accordingly, we conducted research and found that TCGA and CGGA databases indicate a positive correlation between HIF1α, HIF2α, and IGF1R expression in glioma tissues." (PMID 40290443, 2025). "Mechanistically, HIF‐1α targeted NIBAN2 to upregulate it, thereby promoting glioma progression by stimulating the JAK2/STAT3/c‐Myc signaling axis." (PMID 40944417, 2025). "Serum GAL-1, -3, -8, ITGβ-1, HIF-1α, MMP-2, and − 9 levels significantly differed between the glioma and healthy control groups." (PMID 40512281, 2025). "In gliomas, we documented brain-specific immunomodulatory impact of the WWOX/HIF1A axis, which is also context-dependent." (PMID 41007296, 2025).